CD4 (CD4 molecule)
Diseases named in the same sentence as CD4 in open-access papers (continued):
Sharing a sentence is not in itself a finding about the gene and the disease.
glioma (continued). "Four immune cell subtypes (CD4+ naïve T cells, monocytes, macrophages M0 and activated NK cells) to be expressed differently between the two groups (H-ASPHD1 and L-ASPHD1), so immune infiltration may play a role between ASPHD1 and glioma." (PMID 41551155, 2025). "Moreover, canine glioma cells increased CCL2 mRNA expression when exposed to Tregs but not CD4 + helper T-cells." (PMID 39046599, 2024). "Immunoinfiltration analysis indicated that TK1 expression might play different roles in low-grade glioma and glioblastoma multiforme tumor microenvironments, but TK1 expression was positively associated with activated CD4 and Th2, regardless of tumor grade." (PMID 36831773, 2023). "Stimulated PBMCs from healthy donors with anti‐CD3, anti‐CD28, and IL‐2 with glioma stem cell‐derived exosomes significantly inhibited T cell activation, proliferation, and Th1 cytokine production but enhanced purified CD4+ T cell proliferation without affecting cell viability." (PMID 37170647, 2023). "Furthermore, in gliomas, which include GBM and LGG, ORC6 expression was negatively correlated with the abundance of infiltrating immune cells, including Tem CD8, Tcm CD4, Tfh, Th1, Th17, Act B, lmm B, NK, MDSC, NKT, Act DC, pDC, iDC, macrophage, eosinophil, mast, monocyte, and neutrophil cells." (PMID 37901236, 2023). "Injection of their isolated EV containing fraction into a subcutaneous glioma rat model led to an immune-mediated tumour reduction through apoptosis, an increase in tumour infiltrating CD4/CD8 lymphocytes, no change in blood/spleen lymphocytes and few other immune cell alterations." (PMID 37798728, 2023). "Results from our analyses indicated that high CLU expression positively correlated with the infiltrating abundance of different immune cells, such as macrophages, DCs, and CD4+ T cells, which suggest that CLU might modulate the recruitment of immune cells in TME of gliomas to some extent." (PMID 37686218, 2023). "To verify that the transplanted CD8+ T cells were responsible for this glioma-protective capacity, we challenged these SCID survivors with glioma cells combined with αCD8, αCD4, or αAsialo-GM1 antibodies to deplete CD8+ T cells, CD4+ T cells, and natural killer (NK) cells, respectively." (PMID 36759517, 2023). "Experiments in glioblastoma have shown that blocking canonical WNT signaling enhances CD4+/CD8+ immune cell infiltration in the TME, dramatically improving sensitivity to PD-1 therapy in gliomas while igniting ‘cold tumors’, suggesting that WNT3A may be a risk factor for immunotherapy." (PMID 36358276, 2022). "Therefore, BTN2/3 subfamily expression could possibly promote the development of pan-glioma by enhancing PD1 expression interacting with PDL1 and inhibiting CD4 and CD8 T-cell differentiation by upregulating CTLA4." (PMID 36033440, 2022). "Most of the immune cell infiltration scores for CD8 T cells, CD4 T cells, subtypes of dendritic cells, and macrophages were higher in IDH-wildtype samples compared to IDH-mutant samples, which is similar to previous findings in primary gliomas from The Cancer Genome Atlas (TCGA) dataset." (PMID 34885201, 2021). "Additionally, DEXs loaded with chaperone-rich cell lysates (CRCLs) derived from GL261 glioma cells promoted proliferation and activity of CD4+ and CD8+ T cells, enhanced T cell infiltration in intracranial glioma tissues, and induced the generation of anti-tumor cytokines, including IL-2 and IFN-γ." (PMID 34513718, 2021). "However, the lower CD4/CD8 ratio and the scarcity of myeloid cells in the GBMwt_lo gliomas could make them more prone to respond to different immunotherapies not only based on the PD-1–PD-L1 axis." (PMID 33147752, 2020).
glioma (continued). "The results showed that MSCs can be genetically engineered to express cytokines and augment the immune response via enhancing CD4+ and CD8+ T-cell infiltration and then stimulating subsequent cascade immune networks; these modified MSCs can be exploited to a therapeutic advantage against gliomas." (PMID 30143053, 2018). "However, the influences CD4+ Th2 and CD4+FOXP3+ Treg cells have within the TME have not been fully clarified in glioma." (PMID 32914058, 2018). "Nevertheless, these data support negative roles of CD4+ population subsets in glioma progression." (PMID 32914058, 2018). "The ratio of TIL CD4+ and CD8+ T cells in the brain as well as bone marrow was evaluated three weeks after tumor implantation in untreated, systemic-treated, and combined-treated glioma-bearing mice to assess the effect of Tregs depletion on the expansion of CD8+ T cells infiltrating the glioma." (PMID 20339520, 2009). "Furthermore, the percent of PBMCs displaying p-STAT-3 in glioma patients was not directly correlated with the fraction of Tregs in the CD4 compartment." (PMID 19900287, 2009). "In brain cancer, we found that the average FPM of CD4+ T cells, M1-like monocyte-derived macrophages (MDM) and other (not CD8 + or CD4+) T cells is higher in primary gliomas as compared to in brain metastases." (PMID 41446806, 2025). "In contrast, in lower-grade gliomas (LGG), LSM2 expression showed a positive correlation with tumour purity and CD4+ T cell infiltration, but a negative correlation with CD8+ T cell infiltration." (PMID 40365337, 2025). "Taken together, these results suggest that M002 treatment significantly expanded tumor-specific CD4+ T cells and enhanced the tumor-killing capacity of CD4+ T cells, but not CD8+ T cells, in our glioma models." (PMID 39885128, 2025). "In turn, activated CD4+ Tc in PB and CSF, activated CD8+ Tc in CSF, and Bc in PB and CSF were higher in IDH-WT glioma than in antibody-negative ALE." (PMID 39497174, 2024). "Activated CD4+ and CD8+ Tc were increased in the PB of IDH-WT glioma but not in RRMS patients compared to SD controls." (PMID 39497174, 2024). "In our glioma samples, this observation suggested the existence of CD8+ T cells rather than naive or CD4+ T cells." (PMID 39257581, 2024). "Correlatedly, in subcutaneous mouse GL261 gliomas, the MAP4K1-KD group exhibited increased intratumoral infiltration of CD8+ T cells, rather than CD4+ T cells, compared with that of the NC groups." (PMID 37734869, 2023). "The activated CD4+ T cell and CD8+ cytotoxic lymphocyte selectively target tumor cells, whereas the glioma cells that do not express the antigen are targeted by activated NK cells, reducing the chance of cancer immune evasion (#NCT02060955)." (PMID 33803885, 2021). "Neither the percentage of CD19+ B cells, CD3+/CD8+ T cells, CD4+ and CD8+ Tregs nor any of the NK-like T cell subsets differed significantly in patients with gliomas in grade II, III, IV and healthy controls (data not shown)." (PMID 34079819, 2021). "Unlike CD4+ cells, there is appreciably more knowledge surrounding the mechanisms by which CD8+ cytotoxic lymphocyte (CTL) populations affect glioma progression." (PMID 32914058, 2018). "We observed that anti-PD1 therapy effectively reduced the expression of PD-1 on CD4+ and CD8+ lymphocytes in the glioma TME, but no additional effects of combined siGal-1 treatment." (PMID 28450700, 2017). "The data show that glioma specific CD4+ IL-9+ T cells were induced in glioma-bearing mice after treating with SEB and glioma extracts, but not in those treated with either SEB alone or glioma extracts alone." (PMID 28002799, 2017). "We also found that CCR2+/CX3CR1+ M-MDSCs express iNOS in the glioma microenvironment and inhibition of NOS with L-NMMA could recover in vitro proliferation of CD8 T cells, but not CD4 T cell proliferation." (PMID 39272914, 2024).
glioma (continued). "In some studies, increased CD8+/CD4+, CD4+/CD8+, CD3+/Treg, or CD8+/Treg ratios, rather than the absolute counts of individual populations, were correlated with survival outcomes in patients with glioblastoma/glioma." (PMID 38481999, 2024). "For example, one study reported that the number of CD8+ TILs alone could not predict survival of patients with glioma, whereas the combination of having both low density of CD8+ and high density of CD4+ predicted survival." (PMID 35619699, 2022). "In the GL261 murine glioma model, low expression of CD44 and CD122 was found in CD4 + and CD8 + T cells, but an increased proportion of CD44 + T cells was found in double-negative (CD4 - and CD8 -) T cells." (PMID 33381460, 2020). "Moreover, co-administration of anti-CTLA-4 antibody and Treg depletion was used to reverse the tumor immune tolerance, further strengthened CD4+ and CD8+ effector T cells, and resulted in complete glioma eradication without autoimmunity." (PMID 27756892, 2017). "However, it is unclear whether CCL5 in gliomas would also trigger similar Treg inhibition toward CD8+ TILs, as we only found a negligible population (<2%) of Treg characterized as Foxp3+ CD4+ (data not shown)." (PMID 31649684, 2019). "However, unexpectedly, we observed that if MLV-B cores are pseudotyped with either the MCN or MCR HIV-2 Envs they both result in a restricted phenotype in HeLa/CD4 cells, but not in the NP2/CD4/CXCR4 (a permissive glioma cell line stably transduced with the HIV receptors) cells." (PMID 20929586, 2010).
anemia (382 papers, 2007 to 2026). A reduction in the number of red blood cells, the amount of hemoglobin, and/or the volume of packed red blood cells. "Fever, weight loss, spleen and liver enlargement, anemia, hypergammaglobulinemia, and progressive suppression of the CD4+ total and CD4+Leishmania-specific cellular immune response characterize human VL." (PMID 40666521, 2025). "Higher CD4 cell count at enrollment was significantly associated with a lower odds of mortality (unadjusted odds ratio, 0.69 [95% CI.55–.87]), and anemia was associated with a significantly greater odds of mortality (4.86 [1.71–13.81])." (PMID 39906320, 2025). "Male sex, recent initiation of ART, CD4 count < 200, and anemia were independent risk factors for death in both cohorts." (PMID 39901186, 2025). "For example, patients with low CD4 counts (< 200 C/mm3 and/or 200–500 mm3) had a higher susceptibility to develop anemia compared to those with CD4 counts > 500 mm3 (p = 0.019)." (PMID 40809818, 2025). "There were few deaths among participants during follow-up, and 2 baseline laboratory characteristics were significantly associated with death—CD4 cell count and anemia." (PMID 39906320, 2025). "The significant association between anemia and low CD4 count confirms the findings of other studies." (PMID 40809818, 2025). "Older age, CD4 cell counts <200 cells/ml, the presence and severity of anemia, and eCrCl <90 ml/min were associated with a higher risk of discontinuing TDF from the ART regimens." (PMID 38175824, 2024). "From multivariable Fine and Gray regression models, risk factors for discontinuing TDF were older age, CD4 cell count <200 cells/μl, presence and severity of anemia, and eCrCl <90 ml/min." (PMID 38175824, 2024). "HIV-infected people with low CD4+ cell count, high erythrocyte sedimentation rate, and vitamin D deficiency was identified the main predictors of anemia." (PMID 37234694, 2023). "In this subgroup of patients, third-trimester anemia was associated with detectable VL at 34 weeks (p = 0.001), baseline and 34-week CD4+ cell counts (p = 0.002 and p = 0.003, respectively), and trimethoprim-sulfamethoxazole intake (p < 0.001)." (PMID 36870111, 2023). "Longer duration of HIV infection, advanced clinical stage, lower CD4 cell count, and BMI are risk factors for anemia." (PMID 38085717, 2023). "Rural place of residence, WHO clinical stage III/IV, presence of TB coinfection, and low baseline CD4 cell count were reported as positive predictors of HIV-associated anemia in one and/or more of these studies." (PMID 37234694, 2023). "Other studies have demonstrated that anemic patients frequently have weight loss and lower CD4 counts, which supports the conclusion that anemia is related to more advanced forms of TB and HIV." (PMID 37143662, 2023). "In HIV-infected adults, having a CD4 cell count below 200 cells/mm3 raised the risk of anemia by 4.32 (95% CI: 2.10–8.86, P< 0.001)." (PMID 38085717, 2023). "Evidence has reported that lower CD4+ T cell count is associated with poor immune recovery, active viral replication and advanced disease, which are all contributing factors to anemia." (PMID 37858044, 2023). "In line with our finding, having a CD4 cells count below 200 cells/mm3 has increased the risk of anemia by 2.15-fold (95% CI: 1.21–3.82) and 4.2-fold (95% CI: 2.03–8.67) in Wolaita Sodo and Zewditu Memorial Hospital, respectively." (PMID 38085717, 2023). "In the data set restricted to 9 clinics for which hemoglobin data were available, anemia was strongly associated with increased rate of hospitalization/death after adjustment for sex, age, CD4 count, BMI, LAM, TB-related symptoms, and district." (PMID 35855000, 2022). "After adjustment for other confounding factors, risk of anemia was significantly associated with low baseline CD4 cell count (AOR 1.80, 95% CI 1.05–3.06) and tenofovir based regimen (AOR 2.05, 95% CI 1.31–3.21)." (PMID 35333889, 2022).
anemia (continued). "At multivariate analysis, anaemia was associated with being underweight (odds ratio (OR) 2.93, 95% CI 1.70–5.05, P < 0.01), low CD4:CD8 ratio (OR 2.54, 95% CI 1.07–6.04, P = 0.035) and hypochromia (OR 4.23, 95% CI 2.17–8.25, P < 0.01)." (PMID 35022106, 2022). "Factors associated with anaemia at multivariable analysis were low BMI (odds ratio (OR) 2.93, 95% CI 1.70–5.05, P < 0.001), low CD4:CD8 ratio (OR 2.54, 95% CI 1.07–6.04, P = 0.035) and microcytosis (OR 4.23, 95% CI 2.17–8.25, P < 0.001)." (PMID 35022106, 2022). "In HIV-infected individuals, low body mass index, moderate-severe anaemia, low CD4 counts and high CRP were associated with lower physical activity and capacity." (PMID 35061774, 2022). "The experimental data in murine VL showing CD4+ T cells producing IFN-γ with alteration in the stromal microenvironment in bone marrow linked to anemia development reinforced the importance of IFN-γ in the pathogenesis of anemia in active VL." (PMID 34036108, 2021). "Significant associations between severe/moderate anaemia and female sex, malnutrition, low CD4+ count, WHO stage III or IV and VL > 1000 copies/mL were observed using univariate analysis." (PMID 33170905, 2020). "Our results are in agreement with other previously published findings which demonstrated that lower body mass index, higher HIV viral loads, and lower CD4+ T-cell counts are all associated with higher prevalence of anemia." (PMID 33072136, 2020). "Advanced immune suppression at baseline such as an advanced WHO stage, lower CD4 count and anemia were the independent risk factors." (PMID 32374773, 2020). "HIV+TB+ ISUs with CD4 T-cells <200/uL (OR: 2.94, 95% CI: 1.41–6.13, P=0.004) and CD4 Tcells of 200–349/uL (OR: 3.24, 95% CI: 1.66–6.31, P=0.001) associated with higher odds of developing anemia." (PMID 33911826, 2020). "Given the lower CD4 cell counts and higher viral load, anemia has been shown to be associated with worse outcomes." (PMID 33177659, 2020). "In post hoc analyses, we estimated the risk of anemia for subgroups identified as having combinations of high risk characteristics, including CD4 < 100, female sex, and coinfection with HCV." (PMID 32197585, 2020). "CD4 cell count remained a significant risk factor for anaemia among pregnant women pre and post-natally, after adjusting for age, ART regimen and gravidity." (PMID 33425126, 2020). "Older age group (>50 years old), male gender, ZDV based ART regimen, and lower CD4 T cell count were identified as independent factors associated with having cytopenias (anemia, leucopenia or thrombocytopenia)." (PMID 32931523, 2020). "Gender, nutritional status, CD4+ count, and viral load (VL) were associated with anaemia, leukopenia, and thrombocytopenia." (PMID 33170905, 2020). "Conversely, CD4 <200/uL (OR: 2.94, 95% CI: 1.41–6.13, P = 0.004) and CD4 of 200–349/uL (OR: 3.24, 95% CI: 1.66–6.31, P = 0.001) were associated with increased anemia odds." (PMID 33911826, 2020). "For instance, Nevirapine associated hepatotoxicity increases in patients with higher CD4 count while Zidovudine associated anemia and Stavudine associated lipodystrophy is higher in patients with lower CD4 count." (PMID 31060603, 2019). "In a cohort study in Tanzania mortality was 12% among ART patients and was associated with WHO stage III and IV, lower CD4 counts, severe anemia and male gender." (PMID 30653539, 2019). "ART regimen, CD4 count, dietary diversity, educational status and sex were significantly associated with anemia." (PMID 30909968, 2019). "BMI <18.5kg/m2, CD4 count lower than 200cells/ul, years lived with virus and infection with the intestinal parasite were factors associated with anemia among study participants." (PMID 31596865, 2019). "Cox proportional hazard models estimated associations between anemia-type and time to (a) gain at least 100 CD4 cells/L and (b) hospitalization/death." (PMID 30935133, 2019).